NOS2 (nitric oxide synthase 2)
Diseases named in the same sentence as NOS2 in open-access papers (continued):
Sharing a sentence is not in itself a finding about the gene and the disease.
infection (continued). "As expected, bacterial loads were significantly increased in the lungs of H37Rv-infected Nos2−/− mice by day 30 postinfection, but no major differences in lung bacterial loads were observed at earlier times post-H37Rv infection (days 18 and 24 postinfection) compared with WT mice." (PMID 27849167, 2016). "However, high amounts of nitrite were detected in the supernatants of C57BL/6 APECs, but not in their Nos2-/- counterparts, four days after infection." (PMID 26029930, 2015). "Although no significant alterations in the expression of any of the genes were observed between infected and non-infected animals at day 15 post-infection (not shown), at day 60 we could readily detect different levels of Nos2 expression." (PMID 26684322, 2015). "However, in the spleen, the parasite burden was significantly higher in mice lacking Nos2 both at 15 and 60 days after infection, whereas it was only transiently affected by the lack of p47phox (significant difference in parasite load only at day 15)." (PMID 26684322, 2015). "Since IL-12 and NOS2 are strongly, though not exclusively, expressed in activated macrophages, expression levels of several additional genes determining or resulting from particular macrophage polarization were analyzed at day 15 post-infection." (PMID 25919005, 2014). "Similarly, immunohistochemistry analysis revealed that NOS2 positive-cells were almost absent in liver on day 5 post-infection." (PMID 22666512, 2012). "Fungus-induced Arg1 expression in alveolar macrophages was also rapidly induced as early as 6 hours after infection and at none of the time points tested did we detect appreciable NOS2 expression unlike in mice infected with K. pneumoniae that showed brisk NOS2 expression." (PMID 21246055, 2011). "In contrast, CLDC+MPF failed to control SchuS4 infection in macrophages from nos2/gp91−/− mice." (PMID 20523903, 2010). "However, while the NOS2/Arg1 expression ratio remained constantly elevated in DCs isolated from H99γ infected mice at all time points, the CXCL9/FIZZ1 expression ratio peaks at day 7 post-inoculation and declines by day 14, further indicating the infection is being controlled." (PMID 31273203, 2019). "Temporal differences in Nos2 induction following infection with different strains of M. tuberculosis may explain previous reports showing a protective role for NOS2 during the late, but not the early, phase of infection." (PMID 27849167, 2016). "We next infected mice with 50×106 RC to assess expression of AAM-associated molecules at both mRNA and protein levels at time points earlier than 48 hours p.i. to determine whether the expression of Arg1 but not NOS2 was evident from times very early after infection." (PMID 21246055, 2011). "This requirement was enhanced in mice lacking Rag2, Ifng, or Nos2, consistent with the preferential role of ESX1 during the initial stage of infection before the initiation of adaptive immunity, which is prolonged in these immunodeficient strains." (PMID 35112666, 2022). "We observed significantly increased expression of NOS2, but not NOS1 or NOS3, in response to 12 h of SH0165 infection." (PMID 31766159, 2019). "Absence of IL-1R signaling did not affect Nos2 transcription and only slightly reduced NO production by macrophages upon BTB 02-171 infection." (PMID 27849167, 2016). "Absence of IL-10 slightly reduced Nos2 transcription, but it did not affect NO production by macrophages upon BTB 02-171 infection." (PMID 27849167, 2016). "At the end of the treatment period (82 days post-infection) numerous and larger NOS2-positive areas were seen in regions with few or absent AFB, and fewer NOS2-positive cells were found in the areas with increased bacterial load." (PMID 22393444, 2012). "After 40 days of infection, in comparison with noninfected controls wild-type C57BL/6 mice present increased NO levels in serum, which are not detected in Nos2−/− mice (4.4±0.17 μM in noninfected vs. 4.3±2.1 μM in T. cruzi-infected)." (PMID 22590660, 2012).
infection (continued). "To determine whether fenofibrate could exert the same effect in the absence of IL-10 in the single infection model, we assessed the levels of mRNA expression of the M1 markers IL-6, TNF-α and NOS2 in knock out mice." (PMID 33072115, 2020). "In addition, L. major infection induces NOS2 expression by activating TLR4, although ARG1 expression is independent of TLR4 during infection in vivo and in vitro." (PMID 30555476, 2018). "Beside these common markers, some genes were modulated in animals acutely infected by specific strains: Tnf was downregulated by X10 infection, Nos2 for X10 and VFRA, Arg1 for Esm and 10R, while infection with CM17 and Sc43 strains did not lead to modulation of Tgfb1 gene expression." (PMID 28827716, 2017). "Nos2 mRNA, NOS2 protein, and NO secretion were strongly upregulated upon macrophage infection with M. tuberculosis strain BTB 02-171, but not H37Rv, despite similar infection levels, thus replicating the in vivo results." (PMID 27849167, 2016). "Indeed, we did not observe induction of IFNβ and NOS2 mRNA expression in HNEC, and did not detect IFNβ protein and NO in the extracellular media 40 h after HRV14 infection in the absence of activated T cells." (PMID 22022590, 2011). "The addition of IFNγ after infection not only resulted in a dramatic increase of the translation of the before mentioned genes but also in the translation of IFNß1, IL12ß, MIP1 and CCL3, CCL4, NOS2 and SOD2, and FAS but, nevertheless, did not prevent multiplication of the bacteria." (PMID 32462327, 2020).
cancer (171 papers, 1998 to 2026). A tumor composed of atypical neoplastic, often pleomorphic cells that invade other tissues. "For the overall group analysis, patients in Groups 1 and 2 displayed similar expression patterns, particularly the downregulation of cancer-associated genes (Fas, NOS2, VEGF-A, NR4A3, MKi67, and EpCAM), as well as the pro-inflammatory cytokine IL-6." (PMID 40359186, 2025). "The presence of allele A in the NOS2 genotype nearly triples the chances of developing cancer on the right side compared to the left side [OR = 2.72, 95%CI: 1.21–6.08, p = 0.0151]." (PMID 38398251, 2024). "COX-2 is a pro-inflammatory enzyme that is often linked with NOS2 expression in inflammatory conditions and has also been correlated with adverse outcomes in cancer." (PMID 38892290, 2024). "In particular, we are interested in investigating the involvement of nitric oxide synthase 2 (NOS2), an inflammation-associated enzyme with oncogenic function in several cancers, including GBM." (PMID 31226744, 2019). "Since it is well known that NOS activation is regulated by ROS and Reactive Nitrogen Species and that NOS-2 is implicated in human malignant tumors, we investigated the NOS expression." (PMID 31130597, 2019). "Expression of the gene encoding iNOS (NOS2) was analysed using Oncomine Cancer Microarray databases." (PMID 28340615, 2017). "The inflammatory enzyme Nitric Oxide Synthase 2 (NOS2) and its product nitric oxide (NO) have been implicated in the pathophysiology of several inflammatory disorders and human cancers." (PMID 28424427, 2017). "NOS2 was associated with additional cancer biomarkers in these tumors, including pAkt, down stream targets p-caspase-9, and pBAD, as well as the stem cell marker CD44 in ER negative tumors." (PMID 22957045, 2012). "Due to the important role of Nos2 during angiogenesis and cancer-associated immune response, including microglia, stromal effects need to be particularly considered in a systemic Nos2 knockout model." (PMID 22438824, 2012). "The network- and pathway-based analysis indicate that EPO and SPO- specific constituents converge on a shared set of multifunctional genes enriched in inflammatory, oxidative-stress, and cancer-associated signaling pathways, with NOS2 emerging as a common putative core target." (PMID 41598205, 2025). "Given that metastasis is the primary cause of cancer deaths, NOS2/COX2 spatial localization at these sites of inflammation could provide an early prognostic indicator of poor outcome even in the absence of lymph node-positive status." (PMID 37169743, 2023). "For example, Thomas et al33 have shown that NOS2 is highly expressed in different cancers and may be a powerful prognostic biomarker, and NOS2 polymorphisms could be used to predict whether metastatic CRC patients may benefit from first‐line chemotherapy." (PMID 33719152, 2021). "However, the expression level and regulating function of NOS2 varies a lot depending on the cancer type; for example, the downregulation of NOS2 in the subtype 1 of OSCC was associated with the worse survival in the present study." (PMID 34422810, 2021). "The macrophage NOS2 has been implicated in cancer promotion." (PMID 33167555, 2020). "In addition, expression levels of cell cycle (CDK2, CDC2, CCND2) and inflammation markers linked to cancer (NOS2, TGFβ1, CHI3L1 and TFPI) were significantly increased in Caco-2WT/miR-373 compared with Caco-2WT/miR-c, but decreased in Caco-2D299G/α-miR-373 compared with Caco-2D299G/α-miR-c." (PMID 27271572, 2016). "While NOS2 promotes cancer stemness and the formation of metastatic niches, COX2 mediates CD8+ T cell suppression." (PMID 42097035, 2026).
cancer (continued). "This suggests that NOS2 and its substrate arginine are critical components for cancer cell survival and adaptation during anti-KRAS therapies." (PMID 40567499, 2025). "Mutations in the NOS2 gene or its promoter are related to NOS induction and increased rates of different cancers, including esophageal cancer." (PMID 40642105, 2025). "Although NOS2 was initially believed to play antitumor activity, recent data revealed that NOS2 expression in cancer cells frequently correlates with a poor prognosis." (PMID 40743051, 2025). "NOS2 plays a significant role in TNBC progression as high levels of NOS2 expression correlates with poor prognosis, increased metastasis, and cancer recurrence." (PMID 40642105, 2025). "This association of NOS2 and COX2 induction and cancer progression was also observed in in vitro models using NO donors." (PMID 38892290, 2024). "Cancer-derived SPP1 is linked to MDSC (myeloid-derived suppressor cells) immunosuppression by regulating arginase 1, NOS2, VEGF, and IL-6." (PMID 38491408, 2024). "Among NO-associated cancers, TNBC patients who harbor NOS2-expressing tumors have significantly worse prognoses." (PMID 38645113, 2024). "The discovery of NOS2 as a potential ferroptotic biomarker in HB significantly expands our understanding of cancer onset and progression, and has important implications for clinical assessment and treatment strategies." (PMID 37795447, 2023). "There was a significant positive correlation between the expression of the TGF β signaling pathway and NOS2 and between cancer pathways and SLC25A12." (PMID 37954858, 2023). "Some of these genes, such as MAPK, NOS2, CDK2, and TIMELESS, have been previously associated with VIP in non-cancer models." (PMID 37444395, 2023). "A host of evidence highlights that NOS2 is highly expressed in most human cancers, and contributes to cancer stemness, metastasis, chemoresistance, and immunosuppression." (PMID 37795447, 2023). "In comparison to normal tissues, Nos2, Hgf, Lama1, Csf3r, Csf2rb2, Col4a1, Col4a2, Adcy2, Adcy4, Gstm3 and Gstm6 were identified as the most significant genes in cancer pathways." (PMID 37774039, 2023). "As a result, the NOS2/COX2 inflammatory niches increase the potential for cancer cell motility and metastatic spread." (PMID 37169743, 2023). "Collectively, NOS2 was shown to possess cancer-promoting abilities within HB cells, significantly influencing their migration and invasion capacities." (PMID 37795447, 2023). "Concluding, our results confirmed that oxidative stress, especially NOS2 polymorphisms and changes in the expression and methylation of the promoters of SOD2 and NOS2 are involved in the cancer transformation initiation of the cell urinary bladder." (PMID 37660159, 2023). "Both STAT3 and NOS2 targets were directly associated with HIF-1 signaling pathway, which played a crucial role in defending the cancer attack." (PMID 35216171, 2022). "NOS2 is the only isoform to maintain the levels of NO and playing both procarcinogenic and anticarcinogenic roles in different cancers." (PMID 33815659, 2021). "HuR was found to stabilize and increase nitric oxide synthase 2 (NOS2) expression in carcinomas of the lung and colon." (PMID 34638733, 2021). "Most of the genes in the subnetworks were inflammatory cytokines and participated in TNF signaling pathways and pathways in cancer, such as Ccl2, Ccl20, Csf1, Cx3cl1, Cxcl1, Cxcl3, Il6, Birc3, Map3k8, Nos2, Nfkb2, Tnfrsf1b, and Vcam1." (PMID 33042984, 2020). "Tyrosine modified by ROS and RNS can serve as a stable oxidative stress marker, a prognostic marker in cancer, and as an indicator of NOS2, MPO, or EPO activity and therefore a marker of inflammatory leukocyte-mediated tissue damage." (PMID 33167555, 2020). "Since metabolic changes occur during cancer development, we checked the modulation of Arg-1, NOS-2 and COX-2 expression, three key enzymes involved in tumorigenesis." (PMID 32138292, 2020).
cancer (continued). "Conversely, the prevalence of macrophages with M1-like phenotypes expressing IL-12, Tumor Necrosis Factor alpha (TNF-alpha), and Nitric Oxide Synthase 2 (NOS2) has been reported to correlate with favorable clinical outcomes in many human cancers." (PMID 33374253, 2020). "NOS2 is an antitumor component as part of the immune response, which has a low expression in cancer." (PMID 32986356, 2020). "The network surrounding Il10ra shows that many of them are cancer related, e.g., Reg3g, Aoc1, Mep1a, Irf7, Gas6, B3gnt7, Tap1, Tgm2, and Nos2." (PMID 33396408, 2020). "Other inflammatory mediators involved in CRC, such as TNFα and NOS2, were also inhibited by Emodin during the progression from inflammation to carcinoma, through transcriptional regulation." (PMID 33489875, 2020). "Further, we observed that LIUS has the tendency to induce antioxidant effects in non-cancer cells by attenuating the gene expression of NOS2 and NOS3, which promote ROS generation, while promoting the expression of antioxidant genes GPX3 and GPX7." (PMID 31355136, 2019). "Since it is recognized that in several cancers the pro-tumoral effects are directly correlated with the NOS-2 activity, an aggressive cancer biomarker, its level expression was also investigated." (PMID 31683688, 2019). "The effect on pERK kinase results in activation of cytotoxic T cells and the lowering of NOS2 expression, which is known to impair the function of myeloid derived suppressor cells, thus favouring anti-cancer surveillance." (PMID 29304116, 2018). "In this study, NOS2 was predicted to participate in anti-apoptosis-related functions and was found to be significantly enriched in the calcium pathway and cancer pathway." (PMID 28095896, 2017). "LCK and HLA-A displayed similarly positive correlations in both cancers with all markers except NOS2 (iNOS), which was observed only in the two PDAC data sets." (PMID 27762323, 2016). "To examine the role of NO synthesis in ovarian cancer growth in vivo, we treated PDLIM-2-repressed OVCAR-3 and Caov-3 cancer cells with NOS2 siRNA or control." (PMID 26593252, 2016). "Although our analysis identified NOS2 as a hub in the cancer module, it was highly upregulated in responders, while the majority of genes in that module were downregulated, suggesting a reciprocal relationship with other genes in the module." (PMID 26193793, 2015). "The Chi-squared test was applied.Results: Six out of the eleven HNM from carcinoma samples showed positive NOS2 activity whereas all the control group samples yielded negative (p=0.005)." (PMID 24316703, 2014). "To assess the prognostic impact of macrophage infiltration, we compared overall cancer-specific survival in patients with different scores of infiltrating NOS2+ or CD163+ macrophages." (PMID 23077543, 2012). "NOS2+ macrophage infiltration showed a significant effect on cancer-specific survival in CIMP-low cases (P = 0.011)." (PMID 23077543, 2012). "The application of NOS2 as a predictive biomarker and drug target is rapidly emerging as an attractive candidate in cancer therapy." (PMID 22957045, 2012). "NOS2 generates higher levels of NO, and appears to be a better cancer biomarker than the other NOS isoforms, NOS1 and/or NOS3, which are both constitutively regulated and generate low NO flux." (PMID 22957045, 2012). "Nitric oxide (NO) generated by the inducible NO synthase (NOS2) isoform is an important pro-inflammatory mediator linking chronic inflammation with cancer progression." (PMID 22957045, 2012). "When SR/CR Nos2-/- macrophages and neutrophils were transferred into cancer-sensitive WT mice, the SR/CR Nos2-/- cells proved to be less protective against an S180 challenge compared to cells from SR/CR Nos2+/+ mice." (PMID 20356394, 2010).